MYB (MYB proto-oncogene, transcription factor)
Diseases named in the same sentence as MYB in open-access papers (continued):
Sharing a sentence is not in itself a finding about the gene and the disease.
cancer (continued). "In fact, in addition to our above treatment strategies for MYB, ncRNAs mentioned in this review can also be used as a target for cancer treatment." (PMID 34876130, 2021). "In this review, we focus on the complex crosstalk between ncRNAs and MYB in the pathogenesis and development of cancers." (PMID 34876130, 2021). "MYB proteins are highly conserved DNA-binding domains (DBD) and mutations in MYB oncoproteins have been reported to cause aberrant and augmented cancer progression." (PMID 34921182, 2021). "Many studies have shown that MYB participates in the regulation of miRNA expression and is involved in the pathogenesis and development of various forms of cancer." (PMID 34876130, 2021). "MYB is often overexpressed in malignant tumors and plays a carcinogenic role in the initiation and development of cancer." (PMID 34876130, 2021). "Our study demonstrated a novel mechanism underlying the inhibitory effect of LAs on cancer cell proliferation, migration, and invasion, mediated via the DANCR-miR-187-5p-MYB regulatory axis." (PMID 35096852, 2021). "The MYB proto-oncogene has been widely accepted to act as a crucial oncogenic driver of many cancer types, including PAC." (PMID 34314382, 2021). "MYB is involved in cancer progression and has become an important target of various miRNAs, such as miR-423-5p and miR-143-3p." (PMID 34876130, 2021). "In this review, we will highlight studies linking the activity of MYB family members to human malignancies and experimental therapeutic interventions tailored for MYB-expressing cancers." (PMID 33637673, 2021). "Experiments have shown that miR-200 inhibits the expression of MYB, reversing the drug resistance of cancer cells to tamoxifen." (PMID 34876130, 2021). "The expression of MYB in cancer is regulated at the level of alternative splicing, transcription, translation." (PMID 34876130, 2021). "This function stems from the inactivation of molecules in phosphatidylinositol 3-kinase (PI3K)/AKT signaling, repressing MYB expression and retaining the responsiveness of cancer cells to cisplatin." (PMID 33850634, 2021). "In recent years, several approaches have been attempted to inhibit abnormal MYB expression in cancer cells." (PMID 34876130, 2021). "Identification of MYB molecular biomarkers predictive of cancer progression can be used for improving cancer management." (PMID 34921182, 2021). "Overall, these results suggested that SP1 activated ABCC1 and stimulated the expression of the CCNE1, ERF, and MYB genes, which have been shown to be related to chemoresistance and cancer relapse." (PMID 31118037, 2019). "While only the viral, truncated form of c-MYB, v-MYB, appears to be a bona fide oncogene, the normal cellular counterparts are also implicated in cancer development, although their roles remain incompletely understood." (PMID 30833639, 2019). "Gene silencing experiments are also necessary to demonstrate that MYB expression is required for the survival of cancer cells with genetically activated MYB." (PMID 30189404, 2018). "Here, we introduce an alternative approach to interfere with the activity of transcription factors and their aberrant co-activation in cancer by disrupting the interaction of the transactivation domain of MYB with the KIX domain of its coactivator CBP/P300." (PMID 29317678, 2018). "Most importantly, through modulating the STAT3 and AKT pathways, NDRG2 can play an anti-cancer role downstream MYB/miR-130a in SACC." (PMID 30206227, 2018). "The subnetwork of hsa-let-7e retrieved from pan-cancer FFLs includes 57 target genes and 12 TFs including many cancer-related genes such as MYB, E2F2 and HAND1." (PMID 24205155, 2013). "Gains of CFA1 were also detected in studies of other dog cancers and the proto-oncogene MYB has been mapped to this chromosome." (PMID 24098698, 2013). "For example, three members of the TF family MYB: MYB, MYBL1 and MYBL2, appear to be closely associated with cancer." (PMID 22041030, 2011).
cancer (continued). "As briefly reviewed in the Introduction, and more extensively elsewhere, MYB is essential for the proliferation of multiple cancer and normal cell types, including haemopoietic, colonic and mammary epithelial." (PMID 20659323, 2010). "However, with the development of MYB‐targeted inhibitors and the use of MYB‐targeted cancer vaccine therapy, MYB is becoming an increasingly attractive therapeutic target." (PMID 39828507, 2025). "In addition to its functions in cancer progression, MYB is also involved in the developmental process of neural tissues, colonic crypts, breast tissue as well as hematopoietic system." (PMID 40234694, 2025). "Importantly, the cancer cell lines with higher expression levels of MYB exhibited an even greater dependence on the MYB gene for many types of cancer, including COREAD and STAD (Fig. EV2B)." (PMID 40234694, 2025). "MYB activates the hedgehog signaling pathway and thus manipulates cancer progression." (PMID 40888643, 2025). "Herein, we analyzed single cell (n = 4) and high-resolution spatial transcriptomics samples (n = 5) to characterize cancer cell populations in MYB- and non-MYB-expressing cell states, delineated gene expression signatures, and identified critical molecular interactions specific to SGACC." (PMID 40950184, 2025). "MYB proteins play a crucial and versatile role in cancer drug resistance." (PMID 38835346, 2024). "Another important issue is the long-term effect of MYB inhibition on the cancer cells." (PMID 38542205, 2024). "However, drug resistance formation and insensitive cancers warrant a closer look at mechanisms mediated by MYB proteins." (PMID 38835346, 2024). "The remarkable effect of AhR agonists on IGF signaling might also be applicable for combination therapies with IGF-1R inhibitors in other MYB-dependent cancers such as ACC." (PMID 38835346, 2024). "However, the relevance of MYB proteins for human cancer diseases, in particular for solid tumors, remained basically unrecognized for a very long time." (PMID 38835346, 2024). "In addition, MYB-targeting efforts have already revealed several promising anticancer drug candidates for the treatment of various cancers, including strongly MYB-dependent AML and ACC." (PMID 38835346, 2024). "Overall, MYB is overexpressed in most cancer types via the analysis of the data from TCGA and GTEx." (PMID 36994664, 2023). "Interestingly, a weak, but positive, correlation between MYB and AR (r = 0.15, p = 0.00074) was also reported at the transcripts level in publicly available The Cancer Genome Atlas dataset." (PMID 38089573, 2023). "Furthermore, in ACC cells, MYB is able to promote the migration and invasion of cancer cells through the upregulation of VEGFA and ICAM-1, and by increasing MMP7 and MMP9 expression." (PMID 37511133, 2023). "ETV6-NTRK3 and MYB-NFIB have been established to be cancer drivers." (PMID 37744342, 2023). "Further investigations may thus establish MYB as an attractive target for both cancer prevention and therapy." (PMID 38089573, 2023). "To further explore the role of MYB in human cancer, we conducted a pan-cancer analysis of MYB." (PMID 36994664, 2023). "Additionally, the expression level of MYB in normal tissues and cancer cell lines was identified via BioGPS database." (PMID 36994664, 2023). "In addition, MYB expression is significantly related to immune score and immune cells in most cancer types." (PMID 36994664, 2023). "Therefore, we studied the relationship between MYB expression and immune checkpoint genes in human cancers to access the potential of MYB in immunotherapy." (PMID 36994664, 2023). "We propose that overexpressed MYB, seen in multiple cancers, may drive this autoactivation loop and contribute to oncogenic activation of MYB." (PMID 37468105, 2023).
cancer (continued). "Furthermore, the clinical evidence shows a better overall survival for patients with cancer of a specific group with high MYB expression and an enhanced mesenchymal phenotype, which correlates well with the findings in the MC38 model." (PMID 37478172, 2023). "On the contrary, the expression of MYB is lower in cancers such as LUAD, HNSC, PCPG and KICH." (PMID 36994664, 2023). "In addition, we conducted Kaplan–Meier analysis to verify the impact of MYB expression on patient prognosis in several cancers." (PMID 36994664, 2023). "Together, MYB may act as a cancer-promoting gene or a cancer-suppressing gene in different cancer types." (PMID 36994664, 2023). "We therefore asked whether overexpressed MYB correlates in the cancer patient cohorts with higher expression of targets enhanced by 2KR-MYB in K562 similar to the analysis we did with SENP1 expression above." (PMID 37468105, 2023). "Next, we found that the expression level of MYB is significantly higher in most cancers." (PMID 36994664, 2023). "In humans, deletions in MYB are rare, but overexpression is common in several types of cancers." (PMID 37468105, 2023). "MYB emerged as one of the key regulators of this anti-cancer activity." (PMID 35600365, 2022). "Influenced by the secreted signal of lipid-modified glycoprotein, the dysregulation of protein LRSAM1 could inhibit downstream protein MYB, indirectly reducing the motility of cancer cells." (PMID 35164166, 2022). "The ability of HPV integration to alter expression of nearby human genes (within 500 Kb) has been demonstrated in both OPSCC and UCSCC with recurrent integration sites identified near genes implicated in cancer such as MYC, MYB, PVT1, RAD51B, EMBP1, CD274/PD-L1, and SOX2." (PMID 36139648, 2022). "Moreover, MYB silencing also attenuated the growth-promoting effect of androgen on PCa cells, suggesting their cooperative role in cancer pathogenesis." (PMID 36410437, 2022). "Indeed, in other cancers, both gene amplification and transcriptional upregulation of MYB have been reported." (PMID 34145334, 2021). "Abnormal expression of lncRNAs may contribute to the occurrence and development of a variety of cancers, and is partly regulated by the transcription factor MYB." (PMID 34876130, 2021). "So far, many reports have revealed that MYB has an influence on cancers." (PMID 34938350, 2021). "Moreover, the compound also exerts pronounced anti-proliferative effects on MYB-NFIB positive ACC cancer cells while related benign PA cells are affected significantly less." (PMID 35008207, 2021). "MYB functions as a proto-oncogene in multiple types of cancers." (PMID 33850634, 2021). "In vitro and in vivo studies indicated that MYB plays an important role in different cancers." (PMID 35096852, 2021). "There are several mechanisms to activate MYB in human cancer." (PMID 34876130, 2021). "Some miRNAs impede the function of MYB, thereby inhibiting cancer cell proliferation." (PMID 34876130, 2021). "In addition, we discuss therapeutic strategies for crosstalk between MYB and ncRNAs to prevent the occurrence and development of cancer." (PMID 34876130, 2021). "MYB inhibits the expression of circHIPK3, and the metastasis of cancer cells can be controlled." (PMID 34876130, 2021). "Previous studies have shown that MYB inhibition can impair the growth, migration and invasion of cancer cells, suggesting that inhibition of MYB may be a potential cancer treatment strategy." (PMID 34876130, 2021). "In addition to cooperating with protein-coding promoters, MYB also enhances the activity of ncRNA promoters to facilitate cancer initiation and metastasis." (PMID 34876130, 2021). "An intriguing finding was that the described non-coding driver leading to MYB creation in T-ALL could be related to a global increased creation probability in APOBEC driven cancer types." (PMID 31109337, 2019).
cancer (continued). "Moreover, the MYB gene is induced in HCMV infected cells resembling the enhanced MYB gene expression in HPV-related carcinoma." (PMID 31766600, 2019). "Thus, MYBMIM offers a pharmacologic strategy to block leukemogenic transcriptional coactivation as a therapy for AML and other human cancers with aberrant MYB or CBP/P300 activities." (PMID 29317678, 2018). "MYB regulated cancer proliferation and invasion in HCC, and we chose it for further study." (PMID 30133116, 2018). "In addition to MYC, another two cancer-related molecules MYB and MS4A3 were also significantly down-regulated by all five shikonin derivatives." (PMID 26472107, 2015). "c-MYB is a proto-oncogene protein belonging to the MYB (myeloblastosis) family of transcription factors, which directs multiple steps of early lymphoid development and is implicated in human leukaemogenesis and other cancers." (PMID 25232701, 2014). "Therefore, the identification of a recurrent MYB:NFIB translocation in ACC offered a new opportunity to study MYB biology in a defined epithelial human cancer model system." (PMID 25587024, 2014). "However, these genomic alterations can only account for MYB expression in a subset of cancers." (PMID 40234694, 2025). "Therefore, we examined the lineage specificity of the candidate MYB-SE in other cancer types." (PMID 40234694, 2025). "In addition, we found that MYB can bind to SEs of other cancer-related genes." (PMID 40234694, 2025). "In addition, new drug candidates targeting MYB transcription factor activity and signaling have emerged as a promising class of potential anticancer therapeutics that could tackle MYB-dependent drug-resistant cancers in a more selective way." (PMID 38835346, 2024). "We expanded this analysis and used the same TCGA approach to evaluate the broader picture of target genes found to be affected by the SUMO status of MYB in our model cell line K562, well aware of the many perturbations that may influence the expression profiles in cancer patients." (PMID 37468105, 2023). "Thus, a systematic pan-cancer analysis of MYB still remains urgently needed to determine whether MYB could serve as a biomarker for cancer screening, prognosis prediction and accurate therapy design in various human cancers." (PMID 36994664, 2023). "However, miR-150 downregulation facilitates cancer cell migration by increasing MYB expression." (PMID 37924077, 2023). "Interestingly, this analysis revealed that the MYB mRNA level was strongly reduced in the basal cancer subtype, and those of MYBL1 and MYBL2 increased, compared to the levels in normal tissue, partially in line with our finding that p95HER2 expression shifts the miRNA profile towards this subtype." (PMID 30833639, 2019). "As MYB activity is regulated by an interplay with various partner proteins such as CBP/p300 co-activator, disruption of their physical associations might pose as another promising approach to reduce MYB activity in cancer." (PMID 27533466, 2016). "Using this assay, we also detected the known interaction between RUVBL1/2 and MYC47, as well as interactions with other cancer-promoting TFs, including POU2F3 and MYB." (PMID 41241675, 2025). "The expression and dependency of MYB in a subset of COREAD and STAD cancer cell lines are shown in Fig. EV2C." (PMID 40234694, 2025). "Of note, cancer treatment with certain drugs such as HDAC and kinase inhibitors, ATRA, and etoposide, which modulate MYB protein expression or activity as part of their anticancer activity, also revealed MYB-mediated resistance mechanisms." (PMID 38835346, 2024). "Taken together, miR-34a is an important regulator of leukemogenesis through different mechanisms including inhibition of CDK4, MYB, and SIRT1 expression, and/or suppression of B-Myb and E2F1 expression, leading to cell cycle arrest in cancer cells." (PMID 38361758, 2024). "MYB and MYBL1 regulate the expression of cell cycle protein-dependent kinases, which contribute to cancer development." (PMID 38877400, 2024).
cancer (continued). "These 1,670 genes involved well-established cancer-related genes, including MYC, MYB, BRCA2, ERCC4, and MET for s1 subtype and TERT, BCL2, and SUZ12 for s3 subtype." (PMID 36731467, 2023). "Among these 2KR-MYB target genes being also expressed in the respective cancer cohorts, 77.1%, 75.3%, and 67.7% showed a significant correlation between their expression and the expression of MYB in the LAML, BRCA, and COAD cancer cohorts, respectively." (PMID 37468105, 2023). "Next, we identified significantly enriched KEGG (Pathways in cancer and PI3K/Akt signaling pathway) and GO (GO:0000122, GO:0045944 and GO:0045893) terms, and identified eight genes (EDN1, CCND1, MYB, MYC, RUNX1, ITGA6, IL6 and FGF2." (PMID 36978140, 2023). "Although WFA has been reported to have pleiotropic anti-cancer effects, we demonstrate that its anti-AML activity depends on c-MYB modulation and can be partially reversed by a stabilized c-MYB mutant." (PMID 35368048, 2022). "The top-ranked pathways associated with cancer and cell proliferation are highly enriched with the DEGs, such as PIK3AP1, LABM3, AKT1, MYB in “PI3K-AKT pathway” (32%) and “pathways in cancer” (20%)." (PMID 36075900, 2022). "The putative driver fusion (MYB–PCCA–NFIB) and the enhancer hijacking-like mechanism (HIST1H2AG–NonGenic–ERVFRD-1) shed new light on the role of complex SVs and splicing in cancer transcriptomics." (PMID 34811492, 2021). "The majority of the DEGs, e.g., SOX11, TBX21, FAM3B, FGF5, HNF1A, MYB, and PLAC8 have been reported to function as promoters or biomarkers in various cancer types." (PMID 34440579, 2021). "Therapeutic remodeling of complexes of master regulators such as MYB may constitute an effective strategy to reprogram oncogenic gene expression that may prevent or overcome such resistance, providing a platform for therapy of regulatory complex-mediated gene dysregulation in human cancers." (PMID 33527899, 2021). "Some of the other enriched transcription factors include MYB, BRCA1, STAT1 and ETV4 which are upregulated in majority of the cancer types." (PMID 34728699, 2021). "Using the co-culture method, the authors found that exosomes derived from the SGC-7901 cancer cell line transported miR-155 into HUVEC, where they inhibited the expression of c-MYB but promoted the expression of VEGF, a downstream target of c-MYB." (PMID 33233600, 2020). "Previous studies have revealed that MYB-NFIB and MYBL1-NFIB fusions are major alterations in this carcinoma, accounting for approximately 50% and 10% of AdCC cases, respectively." (PMID 29682203, 2018). "In a study employing conditional MYB-NFIB mutant transgenic mice, expression of the oncogene resulted in the development of the carcinoma in nearly 30% of the animals." (PMID 29682203, 2018). "Contrary to MYB, the role of NFIB (Nuclear Factor I B) in normal and cancer cell biology remains obscure." (PMID 27533466, 2016). "This analysis shows that the 1CT7 specific mutated genes are altered in 30.4% of all CRC cases whereas A1309 specific mutated genes are altered in 73.6% of all CRC cases, among which five genes are known cancer genes, i.e. PBRM1, MYB, PRDM16, BCR and NUP214." (PMID 25923178, 2015). "This high-resolution approach enabled a detailed investigation of cancer cell plasticity and intercellular crosstalk between and within MYB and non-MYB expressing cell states." (PMID 40950184, 2025). "In cancer, FOXM1 is generally considered a marker for poor prognosis in cancer survival studies, often as a co-effector with other cancer master regulators, such as CENPF in prostate cancer and MYB in lymphoma." (PMID 39858603, 2025). "We therefore investigated if aberrant activation of MYB in ACC could lead to increased expression of the kinase, promoting cancer proliferation and/or drug resistance." (PMID 38112379, 2024).